CBX3 (chromobox 3)
Diseases named in the same sentence as CBX3 in open-access papers (continued):
Sharing a sentence is not in itself a finding about the gene and the disease.
cancer (continued). "However, the clinicopathological and prognostic value of CBX3 in cancer remains controversial." (PMID 34785774, 2022). "Also, several upstream and target genes of CBX3 had been proved in cancer." (PMID 32894652, 2020). "Moreover, the mechanisms of action of CBX3 in cancer remain obscure." (PMID 31138312, 2019). "Separately, studies have shown CBX3 is an oncogene for many cancers, but the function of CCDC32 in cancers remains to be elucidated." (PMID 39823827, 2025). "CBX3 has been shown to enhance the stemness properties of LUAD cell lines, promoting the expression of cancer stem cell markers and c-Myc targets." (PMID 40175347, 2025). "A functional relationship is known to exist between CBX3 and EGFR or RAC1 in different human cancers, potentially impacting these signaling pathways." (PMID 39272883, 2024). "Collectively, these data suggest that the co-occurrence of CBX3 and EGFR gene amplification is a frequent event in cancer that ultimately leads to an increased expression of both genes." (PMID 37633946, 2023). "We also observed that several CBX members are frequently amplified in cancer tissues, especially CBX1, CBX2, CBX3, CBX4, and CBX8 in LUAD and LIHC tumors." (PMID 36361869, 2022). "For example, the epigenetic transcriptional regulator proteins CBX3 (chromobox homolog 3) and CBX4 (chromobox homolog 4) were up regulated in our cancer samples due to alternative 3’UTRs obtained by gene-fusion." (PMID 28851357, 2017). "The scenario is different for the CBX3 and hnRNPA2B1 bi-directional promoter that results in a highly correlated expression of these two genes in the NCI-60 cancer cell panel including MCF7 and MDA-MB-231 cells." (PMID 26791953, 2016). "Upregulation in cancers was seen in TWISTNB 4, YPEL2 3, CBX3 3, SOX9 8 and β-catenin 7, while downregulation was seen in TWISTNB 6, YPEL2 1, YPEL5 3, SEPT4 2, SEPT6 4, CBX3 3, SOX9 2 and β-catenin 2, compared with those in normal mucosa." (PMID 16504081, 2006). "In contrast, CBX3, CHN1, SULF1 and VDAC1 were significantly elevated in SKCM compared to HD samples, while EDIL3 and PALLD demonstrated significantly lower expression levels in the cancer samples." (PMID 41350567, 2025). "Consistently, we unveiled that the majority of the cancer samples concomitantly expressing the highest levels of CBX3 and EGFR specifically show higher occurrence in EGFR high-grade amplification coupled to low-gain increase in CBX3 gene CN." (PMID 37633946, 2023). "To this end, by using the data from the TCGA Pan Cancer Atlas, we first found that CBX3 gene amplification negatively correlates with patient survival." (PMID 37633946, 2023). "Collectively, our findings indicate that the concomitant overexpression of both EGFR, CBX3 and RAC1 may be an extremely unfavorable general prognosis marker in human cancer." (PMID 37633946, 2023). "Coherently, tumors with CBX3 gene amplification display a low gain increase or high-grade amplification of EGFR gene, thus confirming the evidence that CBX3 and EGFR gene amplification co-occurs in diverse human cancers." (PMID 37633946, 2023). "For the StromalScore, the top 3 cancers with significant differences showed negative correlations with CBX3 expression in TGCT, BRCA, and LUSC." (PMID 35172803, 2022). "Investigation of TCGA (The Cancer Genome Atlas) data set revealed that while Cbx1 and Cbx5 are not regulated, Cbx3 is upregulated in GBM compared to control brain samples, although not due to differential methylation." (PMID 27291091, 2016). "On the other hand, cancer samples from TCGA Pan Cancer Atlas Studies harboring high CN increase in RAC1 gene display enhanced expression of CBX3 RNAs, thus further confirming that gene amplification of RAC1 and CBX3 leads to an increase of CBX3 and RAC1 mRNAs, respectively in human cancers." (PMID 37633946, 2023).
cancer (continued). "Thus, CD8+ T cells heightened effector function consequent to Cbx3/HP1γ deficiency may be distinct from functional reactivation by ICB, implicating Cbx3/HP1γ as a viable cancer T-cell-based therapy target for ICB resistant, non-responsive solid tumors." (PMID 34721405, 2021). "Collectively, these findings indicate that the simultaneous overexpression of CBX3, RAC1 and EGFR could lead to a negative synergistic effect on cancer patient survival." (PMID 37633946, 2023).
gastrointestinal tumors (2 papers, 2024 to 2025). "GI tumor tissues with higher CBX3 K10la intensities exhibited elevated protein levels of hexokinase 2 (HK2), glucose‐6‐phosphate isomerase (GPI), and pyruvate kinase M (PKM)." (PMID 39018247, 2024). "We also found that GI tumors with higher CBX3 lactylation showed proteomic downregulation of oxidative phosphorylation metabolism." (PMID 39018247, 2024).
kidney diseases (1 paper, 2025). "We measured serum anti-SPTBN1 and anti-CBX3 IgA levels in patients with IgAN (n = 119) and other kidney diseases (disease control [DC], n = 51) using 2 independent cohorts, 1 from Japan and 1 from the UK." (PMID 40485707, 2025).
CBX3 also shares sentences with these, for which no sentence is quoted: pancreatic adenocarcinoma (4 papers); infection (3); endometrial carcinoma (2); ganglioneuroblastoma (2); leukemia (2); lymphoma (2); adrenal cortical carcinoma (1); Burkitt lymphoma (1); colorectal tumors (1); gastric cardia adenocarcinoma (1); genitourinary cancer (1); HCMV Infection (1); Hutchinson-Gilford progeria syndrome (1); Hyperoxaluria (1); immune disorders (1); kidney failure (1); kidney tumors (1); low grade glioma (1); malignant fibrous histiocytoma (1); myopia (1); myxofibrosarcoma (1); myxoid liposarcoma (1); myxoid/round cell liposarcoma (1); neurological diseases (1); Oral Squamous Cell Carcinoma (1); paraganglioma (1); pheochromocytoma (1); pleomorphic liposarcoma (1); rectal cancer (1); round cell liposarcoma (1).
A further 10 diseases each share a sentence with CBX3 in 1 paper.